RN7SKP271 (RN7SK pseudogene 271)
Gene: Miscellaneous RNA gene on chromosome 20 (35,643,143 to 35,643,462, forward strand). Ensembl gene ENSG00000222460.
Homologues: Orthologues: chimpanzee 7SK (76% identical). Paralogues in human: RN7SKP90 (71% identical), RN7SKP180 (70% identical), 7SK (70% identical), RN7SKP217 (70% identical), RN7SKP79 (69% identical), RN7SKP203 (69% identical), RN7SKP30 (69% identical), RN7SKP176 (69% identical), RN7SKP189 (68% identical), RN7SKP255 (68% identical), RN7SKP8 (68% identical), RN7SKP146 (68% identical), and 284 more.